PDCD1 (programmed cell death 1)
Diseases named in the same sentence as PDCD1 in open-access papers (continued):
Sharing a sentence is not in itself a finding about the gene and the disease.
cancer (continued). "The immune checkpoint programmed cell death-1/PD-ligand 1 (PD-1/PD-L1) is associated with pro-inflammatory cytokine production and cancer growth." (PMID 35237605, 2022). "Studies have reported that single nucleotide polymorphisms (SNPs) in the PDCD-1 gene can influence cancer risk." (PMID 36009373, 2022). "ICIs were developed against programmed cell death ligand 1 (PD-L1) on cancer cells, and the immune suppressive receptors programmed cell death 1 (PD-1) and cytotoxic T-lymphocyte-associated antigen 4 (CTLA-4) on cytotoxic T cells." (PMID 35844547, 2022). "Increased TOX expression in PBLs from cancer patients was associated with reduced expression of anti-programmed cell death-1 (PD1)." (PMID 36005179, 2022). "Expression in the presence of the wild type PDCD1 rs7421861 “A” allele, the one we have identified as associated with cancer risk, was therefore higher, with the minor allele associated with significant suppression." (PMID 33808740, 2021). "Checkpoint blockade therapies targeting programmed death ligand 1 (PD-L1) and its receptor programmed cell death 1 promote T cell-mediated immune surveillance against tumors and have been associated with significant clinical benefit in cancer patients." (PMID 34887871, 2021). "T1D is observed in cancer patients after anti-PD-1 treatment and occurred in the PDCD1- deficient patient." (PMID 35154081, 2021). "Among them, the cytotoxic T lymphocyte-associated protein 4 (CTLA-4), programmed cell death 1 (PD-1), and PD-1 ligand (PD-L1) received great attention in recent years due to their use in cancer therapy." (PMID 34658896, 2021). "Several genetic association studies had investigated genetic variants of programmed cell death 1 (PD-1) and programmed death ligand 1 (PD-L1) with cancer, autoimmune and infectious diseases in different world populations." (PMID 33833369, 2021). "Programmed cell death-ligand 1 (PD-L1), encoded by the CD274 gene, is the ligand of programmed cell death-1 (PD-1) and exists in several cancers, and it has the ability to inhibit T cell activation." (PMID 34307695, 2021). "Tumor mutational burden (TMB) is a key factor in determining the response of patients with cancer to immunotherapy with immune checkpoint inhibitors (anti-programmed cell death 1 [PD-1] or anti-cytotoxic T lymphocyte-associated antigen 4 [CTLA-4])." (PMID 34335558, 2021). "By contrast, destructive thyroiditis was observed in both the PDCD1-deficient patient and in cancer patients treated with anti-PD-1 antibodies." (PMID 35154081, 2021). "Since this is the first study of PDCD1 and PD-L1 polymorphisms in the context of ccRCC, we believe that our research will broaden current knowledge of the genetic basis of this type of cancer." (PMID 33255938, 2020). "Cytotoxic T-lymphocytes-associated antigen-4 (CTLA-4), programmed cell death-1 (PD-1), and programmed cell death ligand-1 (PD-L1) are well-known immune checkpoint modulators and are implemented for cancer treatment." (PMID 32244307, 2020). "Cancer cells exploit the “immune checkpoint” function to evade the immune system by expression of programmed cell death-1 (PD-1) or anti–cytotoxic T-lymphocyte-associated antigen-4 (CTLA-4) resulting in increased apoptosis of T cells." (PMID 32670880, 2020). "Programmed cell death-1 (PD-1) immune checkpoint blockade is a promising strategy in many types of cancer, but its therapeutic effects in GB remain low and associated with immune infiltration." (PMID 33233585, 2020). "Two meta-analyses investigating the association between PDCD1 SNPs and overall cancer risk, in a subgroup analysis by cancer type (951 patients, 806 controls), indicated an association between PD-1.5 and susceptibility to BC." (PMID 33519815, 2020). "Blockade of immune checkpoints, including the cytotoxic T lymphocyte-associated protein (CTLA)-4 and the programmed cell death-1 (PD-1)/PD ligand-1 (PD-L1) pathway, have increased overall survival and progression-free survival of cancer patients." (PMID 31085177, 2019).
cancer (continued). "The checkpoint inhibitor antibody α-programmed cell death 1 (α-PD-1) mediates profound clinical responses in patients with cancer, particularly in malignancies with high mutational burden." (PMID 31235641, 2019). "Recently, immunotherapy targeting immunosuppressive proteins such as cytotoxic T-lymphocyte associated protein 4 (CTLA-4) and programmed cell death 1 (PD-1) has provided more treatment options for cancer patients." (PMID 28081243, 2017). "Baseline PDCD1 mRNA expression was also associated with progression-free survival after anti-PD-1 therapy in a pooled cohort of cancer patients." (PMID 29255458, 2017). "For the PDCD-1.3 (rs11568821) polymorphism, there was statistical evidence of an association between the polymorphism and overall cancer risk in TC versus TT genetic model (OR = 0.79, 95% CI: 0.65–0.96, P = 0.02)." (PMID 27749524, 2016). "In order to better understand the potential roles of PDCD1 polymorphisms in cancer, further studies with larger sample sizes, combining genetic and other environmental risk factors, are needed." (PMID 27749524, 2016). "The effects of the programed cell death 1 (PDCD1) gene polymorphisms on cancer risk have been investigated in some studies; however, the results were conflicting and ambiguous." (PMID 27749524, 2016). "A total of 24 case–control studies from 13 articles that investigated the associations of 5 widely studied polymorphisms in PDCD1 gene and cancer risks were included." (PMID 27749524, 2016). "The association between PDCD1 polymorphisms with cancer risk was calculated with odds ratios (ORs) and their corresponding 95% of confidence intervals (CIs)." (PMID 27749524, 2016). "The current meta-analysis, which included a total of 24 case–control studies from 13 articles, investigated the associations of 5 widely studied polymorphisms in PDCD1 gene and cancer risk." (PMID 27749524, 2016). "The meta-analysis suggests that the PDCD-1.5 (rs2227981) and PDCD-1.3 (rs11568821) polymorphisms are associated with susceptibility of cancer." (PMID 27749524, 2016). "In this meta-analysis, we had insufficient data to conduct an evaluation of such interactions for the role of PDCD1 polymorphisms and factors in cancer development." (PMID 27749524, 2016). "Immunoinhibitory checkpoint pathways (cytotoxic T lymphocyte-associated protein-4 [CTLA-4]/B7, programmed cell death-1 [PD-1]/programmed cell death ligand-1 [PD-L1]) are emerging as interesting immunotherapeutic targets for the treatment of cancer." (PMID 25935754, 2015). "In conclusion, this study highlights critical insights into how the nsSNPs in coding and non-coding regions within the PDCD1 gene can affect its structure, function, and regulation, indicating their important roles in immune checkpoint modulation and cancer susceptibility." (PMID 40149458, 2025). "Additionally, this study examined the expression profiles of PDCD1 across cancer types and their association with overall survival rates to examine the prognostic value of PD-1." (PMID 40149458, 2025). "In contrast to drug-targeted therapy, immunotherapy uses the body’s own immune system to attack cancer cells and includes immune checkpoint inhibitors such as programmed cell death 1 (PDCD1; also known as PD-1) and cytotoxic T-lymphocyte associated protein 4 (CTLA4) inhibitors." (PMID 39070147, 2024). "Furthermore, PDE2A expression in most cancers was positively associated with PDCD1, EDNRB, ADORA2A, TGFB1, and especially C10orf54." (PMID 39699377, 2024). "However, with reference to present oncology immune checkpoint inhibitors (ICIs) such as anti‐cytotoxic T lymphocyte associated protein 4, (CTLA‐4) and anti‐programmed cell death 1 (PD‐1) are better at treating cancer than traditional chemotherapy." (PMID 38333968, 2024). "Hence, to define gene signatures associated to PDCD1/LAG3 co-expression in human cancers, we performed an extensive analysis of publicly available multiomics cancer data." (PMID 39030301, 2024).
cancer (continued). "By disabling immune checkpoints, such as those regulated by cytotoxic T-lymphocyte-associated protein 4 (CTLA-4) or programmed cell death-1 (PD-1), cancer immunotherapies stimulate the activity of immune cells that can thereby promote the clearance of cancer cells." (PMID 36743451, 2023). "Interestingly, PDCD1 (encoding programmed cell death protein 1), which is considered an immune-inhibitory receptor and provides a new and reliable direction for cancer immunotherapy, was also frequently affected by CNAs in HER2-low TNBC samples." (PMID 37991016, 2023). "Immune checkpoint inhibitors (ICIs), including cytotoxic T-lymphocyte antigen 4 (CTLA-4), programmed cell death 1 (PD-1), and its ligand 1 (PD-L1), have improved the survival in multiple types of cancers; however, ICIs may cause cardiovascular toxicity." (PMID 37305530, 2023). "Within the past decade, T-cell-targeted immunomodulators directed against the immune checkpoints of cytotoxic T-lymphocyte-associated protein 4 (CTLA-4), programmed cell death 1 (PD-1), and its ligand (PD-L1) have revolutionized cancer treatment for several types of tumors." (PMID 36831648, 2023). "Indeed, several studies have shown that alterations in DNA damage response and repair genes are associated with response to programmed cell death 1/programmed cell death ligand 1 (PD-1/PD-L1) blockade in patients with several types of cancer." (PMID 36494792, 2022). "Immune checkpoint inhibitors targeting cytotoxic T-lymphocyte-associated protein 4 (CTLA4) and programmed cell death 1/programmed death ligand 1 (PD1/PDL1) have been used with great success in several cancers and are now widely accepted as one of the standard therapies in cancer treatment." (PMID 36048239, 2022). "Immune-checkpoint inhibitors (ICIs) targeting cytotoxic T lymphocyte-associated antigen 4 (CTLA-4), programmed cell death 1 (PD-1) and its ligand (PD-L1) interaction have shifted the treatment landscape of advanced cancers and significantly improved the overall survival (OS)." (PMID 34248939, 2021). "These strategies consist of neutralizing antibodies against negative immune checkpoints as Cytotoxic T-Lymphocyte Associated Protein 4 (CTLA-4), Programmed Cell Death 1 (PD-1), and PD-1 Ligand-1 (PD-L1), thereby impeding the ability of cancer cells to evade the immune surveillance program." (PMID 34067257, 2021). "Although 49 microRNAs were identified as linked to the CD274/PDCD1 network and many showed survival relationships (with 130 significant survival relationships being identified across fourteen cancer types), it is beyond the scope of this article to validate each of them." (PMID 34067485, 2021). "Finally, the hsa-MiR-204-3p targets the wild PDCD1 -606G allele, and several studies report that this miRNA is a protective factor against cancer development by different cellular mechanisms depending upon the cell origin." (PMID 34290992, 2021). "Immune checkpoint inhibitors (ICIs), such as anti-cytotoxic T lymphocyte-associated antigen 4 (anti-CTLA-4), anti-programmed cell death 1 (anti-PD-1), and anti-programmed death-ligand 1 (anti-PD-L1), have revolutionized the management of malignant tumors, especially those at advanced stages." (PMID 34885219, 2021). "The antagonistic mAbs used in immune checkpoint blockade are able to block T cell-inhibitory signaling from receptors such as cytotoxic T-lymphocyte-associated antigen 4 (CTLA-4) and programmed cell death-1 (PD-1), and have been successfully used in the treatment of several types of cancers." (PMID 31417564, 2019). "Unprecedented rates of long-lasting tumor responses can be achieved in patients with a variety of cancers blocking the immune checkpoints with inhibitors (ICI) such as antibodies targeting cytotoxic T lymphocyte–associated protein 4 (CTLA-4) or the programmed cell death 1 (PD-1) pathway." (PMID 31661001, 2019).
cancer (continued). "Thus, we conducted a comprehensive meta-analysis to investigate the association of PDCD1 gene polymorphisms and cancer risk." (PMID 27749524, 2016). "Therefore, we aimed to do a meta-analysis to investigate the association of PDCD1 polymorphisms with cancer risk from all eligible case–control studies." (PMID 27749524, 2016). "In this meta-analysis, we also found that the PDCD-1.3 (rs11568821) polymorphism was significantly associated with decreased risk of cancer, and the genotype TC might be a risk factor." (PMID 27749524, 2016). "In conclusion, our meta-analysis suggests that PDCD-1.5 (rs2227981) and PDCD-1.3 (rs11568821) polymorphisms are associated with susceptibility to cancer, while rs2227982, rs7421861, and rs10204525 polymorphism may not be associated with cancer risk." (PMID 27749524, 2016). "Variants in PDCD1 may alter its function, impacting cancer susceptibility and disease progression." (PMID 40149458, 2025). "Additionally, nsSNPs in the human PDCD1 gene may affect its functions, especially immune regulation, cancer susceptibility, and therapy response." (PMID 40149458, 2025). "The Cytotoxic T-Lymphocyte Associated Protein-4 (CTLA4) and programmed cell death-1 (PD-1) checkpoint pathways are inhibitory pathways, and blocking these inhibitory pathways with mAbs has triggered antitumor immune responses that altered the cancer therapy field." (PMID 38234663, 2024). "Immune checkpoint inhibitors (ICIs) have been increasingly used in the treatment of several malignancies and may target cytotoxic T-lymphocyte-associated antigen-4, programmed cell death-1, and programmed cell death ligand 1, which work on maintaining peripheral immune tolerance." (PMID 37583508, 2023). "Recently, immune checkpoint molecules, such as cytotoxic T-lymphocyte-associated protein 4, programmed cell death-1/programmed death-ligand 1, and their inhibitors, have attracted significant attention for overcoming the immunosuppressive conditions in patients with cancer." (PMID 35008367, 2021). "Immune checkpoint molecules, such as cytotoxic T-lymphocyte-associated protein 4, programmed cell death-1/programmed death-ligand 1, and their inhibitors, have attracted significant attention for overcoming the immunosuppressive conditions in patients with cancer." (PMID 35008367, 2021). "This was followed by significant advances with the development of anti-programmed cell death 1 (anti-PD-1) or its ligand (anti-PD-L1) mAb, such as nivolumab or pembrolizumab, becoming part of the standard treatment for multiple cancer types." (PMID 41200168, 2025). "Immune checkpoint analysis indicated higher expression of CD274, PDCD1, and other inhibitory molecules, suggesting potential for targeted cancer immunotherapy." (PMID 40963614, 2025). "Overall, these results suggest that blocking circGRAMD4 can improve the effectiveness of PDCD1 blockade, thereby offering a promising avenue for the advancement of cancer immunotherapy outcomes in RCC." (PMID 40373256, 2025). "Immune checkpoint inhibitors (ICIs), including antibodies against programmed cell death 1 and programmed death ligand 1, have revolutionized the treatment of many cancers, including ESCC." (PMID 40065859, 2025). "Our findings demonstrated that PDCD1, a key ICP molecule, and seven other genes, were notably expressed at higher levels in the low‐risk group of cancer patients." (PMID 40747615, 2025). "Cd274 expression in M2d cells and Pdcd1 expression in T cells were decreased when cancer Yap1 was silenced." (PMID 39946200, 2025). "Programmed Cell Death 1 (PD-1; CD279) is the best characterized and studied immune checkpoint receptor in cancer, with PD-1 inhibitors showing strong antitumor activity in several cancer settings including melanoma and Non-Small Cell Lung Cancer (NSCLC)." (PMID 40072074, 2025). "Camrelizumab is a humanized high-affinity monoclonal antibody targeting programmed cell death-1 (PD-1), which has been approved for use across multiple cancer types." (PMID 41550955, 2025).
cancer (continued). "In this context, two key molecular drivers of cancer immune-suppression have been identified: the cytotoxic T lymphocyte-associated protein 4 (CTLA4) and programmed cell death 1 (PD1)." (PMID 40230698, 2025). "SNPs in the PDCD-1 gene significantly influence its protein expression and function, affecting immune regulation and cancer progression." (PMID 40149458, 2025). "Nivolumab is an ICI antibody against programmed cell death 1 (PD-1), and a widely used human monoclonal antibody for the treatment of various cancers." (PMID 41256313, 2025). "In recent years, there has been significant advancement in immuno-oncology (IO) treatments, with monoclonal antibodies (mAbs) targeting programmed cell death-1 (PD-1) now recognized as the standard treatment for various types of cancer." (PMID 40746596, 2025). "Programmed cell death 1 (PD-1) and its ligand (PD-L1) participate in modulating the immune response to cancer." (PMID 40149674, 2025). "Using the GEPIA2 database, boxplots were produced to analyze the expression of the PDCD1 gene and identify its differential expression patterns across different types of cancer." (PMID 40149458, 2025). "We examined the relationship between EIF5A2 and immune checkpoints using Spearman analysis and found that EIF5A2 was correlated with CD274, PDCD1LG2, and HAVCR2 in the majority of cancers and PDCD1, CTLA4, LAG3, SIGLEC15, and TIGIT in some tumors." (PMID 40964657, 2025). "For example, anti-targeting programmed cell death 1 (PD-1) and programmed cell death ligand 1 (PD-L1) monoclonal antibodies enhance the stimulation of the immune system against cancer cells." (PMID 41157055, 2025). "Immune checkpoint therapy has brought a breakthrough in cancer therapy, and the programmed cell death 1 (PD1) antibody has been approved for the treatment of CRCs with high levels of microsatellite instability." (PMID 39759121, 2025). "Pembrolizumab is an immune checkpoint inhibitor (ICI) of programmed cell death-1 category, used for treating various types of cancer." (PMID 40026847, 2025). "Six of these—CD5, CTLA4, TIGIT, LAIR1, PDCD1, and TNFRSF14—encode proteins that have been identified as immune checkpoints, defined broadly as receptors on immune cells that are exploited by cancer cells to escape the immune response." (PMID 39887658, 2025). "Their mechanism of action involves inhibiting cytotoxic T lymphocyte-associated antigen 4 (CTLA4) and programmed cell death 1 (PD-1) on T-cells, or its ligand (PDL-1), leading to enhanced T-cell activation and immune activity against cancer cells." (PMID 40823470, 2025). "Immune checkpoint inhibitors (ICIs), including programmed cell death-1 (PD-1) inhibitors such as nivolumab, have revolutionized cancer treatment and brought survival benefits to patients with advanced melanoma." (PMID 41181814, 2025). "The study demonstrated the potential of this nanovaccine in augmenting T-cell immune responses and cancer immunotherapy, especially when used in combination with anti-PDCD1 antibodies." (PMID 39817564, 2025). "This study also assessed the level of expression of the PDCD1 gene across different cancer types and investigated its relationship with overall survival rates in cancer patients." (PMID 40149458, 2025). "Programmed death 1 ligand (PD-L1), an important immune checkpoint molecule, is mainly expressed on cancer cells and has been shown to exert an immunosuppressive effect on T-cell function by binding to programmed cell death 1 (PD-1) expressed on T-cells." (PMID 40001596, 2025). "Cancer immunotherapy has revolutionized oncology, with immune checkpoint inhibitors targeting the programmed cell death-1 (PD-1)/PD-L1 axis being among the most successful approaches." (PMID 40710508, 2025). "Anti-programmed cell death 1 (PD-1) monoclonal antibodies (mAbs) have proven to be effective in treating various cancers, including colorectal, lung, and melanoma." (PMID 39808627, 2025).